COXFA4P2 (COXFA4 pseudogene 2)
Synonyms: bcm1723; formerly NDUFA4L; NDUFA4P2
Gene: Processed pseudogene on chromosome 3 (103,240,987 to 103,241,230, forward strand). Ensembl gene ENSG00000236691.
Diseases named in the same sentence as COXFA4P2 in open-access papers:
COXFA4P2 is named in the same sentence as 1 disease in open-access papers, as found by Europe PMC text mining. Sharing a sentence is not in itself a finding about the gene and the disease.
COXFA4P2 shares sentences with these, for which no sentence is quoted: asthma (1 paper).